CD69 (CD69 molecule)
Diseases named in the same sentence as CD69 in open-access papers (continued):
Sharing a sentence is not in itself a finding about the gene and the disease.
sarcoma (5 papers, 2022 to 2024). A usually aggressive malignant neoplasm of the soft tissue or bone. "To determine the CC-3 dose required to fully activate T cells in cocultures with sarcoma cells, we titrated CC-3 and determined expression of the activation marker CD69 on T cells by flow cytometry after 24 h." (PMID 38765008, 2024). "In addition, DFMO and GC7 treatment sustained CD69 expression in CD8+ T cells from human sarcoma tumor infiltrating lymphocytes (TIL) following activation with anti-CD3/CD28 and IL-2." (PMID 37581943, 2023). "Analysis of NK cells within PBMC for CD69 expression after 24 h by flow cytometry revealed that 8H8_WT already enhanced NK cell activation, and NK cell activation was further significantly enhanced upon treatment with 8H8_SDIE for all sarcoma cell lines." (PMID 36275693, 2022). "The glutamine/polyamine/hypusine axis controls CD69 expression in human CD8+ T cells, sarcoma TIL, and CAR-T cells." (PMID 37581943, 2023). "We observed the upregulation of early and late T-cell surface activation markers (CD69 and CD25) in experiments performed in three different sarcoma cell lines, such as Rh-30, HT-1080 and CAL-72." (PMID 36980534, 2023). "Importantly, when gated on CD69+CD49a+ or CD69+CD103+ cells, DFMO cotreatment led to increased levels of IFN-γ and TNF-α in post–rapid expansion protocol (post-REP) human sarcoma TIL." (PMID 37581943, 2023). "Interestingly, adding TGF-β to human sarcoma TIL treated with DFMO or with GC7 also enhanced the generation of CD69+CD103+ and CD69+CD49a+ Trm cells." (PMID 37581943, 2023). "Furthermore, blocking the polyamine/hypusine axis augmented CD69 expression as well as IFN-γ and TNF-α production in (a) human CD8+ T cells from peripheral blood and sarcoma tumor infiltrating lymphocytes and (b) human CD8+ CAR-T cells." (PMID 37581943, 2023). "Considering that sarcoma TIL cultures showed successful expansion and proliferation in vitro, it is likely that the subsets of CD4+CD69+ T-cells and CD8+HLA-DR+ T-cells did not impose suppressive actions and that the markers may be indicative of an activated T-cell population." (PMID 35158816, 2022).
type 1 diabetes (5 papers, 2018 to 2025). "Among the 285 disease-associated genes, CD69, PLGRKT, and CD226 have also been implicated in recent genome-wide association studies (GWAS) of type 1 diabetes, highlighting the potential significance of these genes in type 1 diabetes." (PMID 41462339, 2025). "The percentages of T and B lymphocytes expressing CD69 antigens in a group of patients with type 1 diabetes was analyzed in relation to the presence of anti-VCA antibodies in the IgM and IgG classes." (PMID 36768715, 2023). "A statistically relevant higher percentage of CD4+ T lymphocytes expressing the CD69 marker was found in the group of patients with type 1 diabetes than in the control group (p = 0.029)." (PMID 36768715, 2023). "‘The patients with type 1 diabetes were characterized by a statistically significantly higher percentage of CD8+ T lymphocytes expressing the CD69 molecule than the healthy subjects (p = 0.003)." (PMID 36768715, 2023). "Scientists found a higher expression of CD69 and CD25 antigens in patients with type 1 diabetes than in a control group." (PMID 36768715, 2023). "In these women, CD69 expression on MAIT cells was significantly increased compared with healthy women and women with long-term type 1 diabetes." (PMID 34350463, 2021). "Decreased Th1 cytokines and increased CD69, PD1 and IL-4 expression were the major contributors to the segregation of adults with long-term type 1 diabetes from heathy donors." (PMID 34350463, 2021). "Similarly, transcripts of candidate genes for type 2 diabetes (Blk, C2cd4a, C2cd4b, Cdkn2a, Hnf1a, Mtnr1b, Pou5f1, Slc30a8) and type 1 diabetes (Cd69, Il2, IL27) were not expressed in the brain." (PMID 39920851, 2025). "We did not observe any differences in CD69+ MAIT cell frequencies between control donors and participants with recent-onset or long-term type 1 diabetes." (PMID 34350463, 2021).
ulcerative colitis (5 papers, 2017 to 2025). An inflammatory bowel disease involving the mucosal surface of the large intestine and rectum. "In particular, patients with ulcerative colitis exhibit a higher frequency of CD69+ MAIT cells compared to healthy controls, underscoring its role as a marker of immune activation in diseases." (PMID 40025566, 2025). "In ulcerative colitis, MAIT cells are enriched in the colonic mucosa and display increased CD69 expression alongside elevated production of IL-17 and IL-22, correlating with disease activity." (PMID 40025566, 2025).
Alzheimer disease (4 papers, 2011 to 2024). A progressive, neurodegenerative disease characterized by loss of function and death of nerve cells in several areas of the brain leading to loss of cognitive function such as memory and language. "This variation underscores CD69’s role in immune modulation, from influencing regulatory T cell differentiation via the Jak3/Stat5 pathway to its association with Alzheimer’s disease pathology." (PMID 38742110, 2024).
autoimmune thyroid disease (4 papers, 2017 to 2022). Inflammatory disease of the thyroid gland due to autoimmune responses leading to lymphocytic infiltration of the gland. "These CD69+ Treg cells also show an abnormal number and function in patients with different conditions, including autoimmune thyroid diseases, SLE, and liver carcinoma." (PMID 30116758, 2018). "In addition, we have observed that a fraction of this cell subset corresponds to CD4+CD69+ Treg lymphocytes and that patients with autoimmune thyroid disease or SLE show abnormal numbers and function of these cells." (PMID 30116758, 2018). "Expression of LAMP1 and CD69 in thyroid tissues of AITD patients was upregulated significantly, compared to normal thyroid tissues, while TYR was positively stained only in autoimmune thyroid tissues." (PMID 29362715, 2017). "Although the expression of CD69 on naïve CD4+ T cells has been published in some pathological conditions, such as Graves’ disease and autoimmune thyroiditis, no reports were found in Chagas disease." (PMID 36447264, 2022).
Chagas disease (4 papers, 2011 to 2025). A parasitic infection caused by Trypanosoma cruzi. "In our study, a consistent increase in the frequencies of CD69+CD4+ T cells among all T cell subsets was observed during Chagas disease." (PMID 36447264, 2022). "Taken together, these data indicate a higher expression of CD69 in CD4+ T cells in patients with Chagas disease, especially in those in the indeterminate form (A) and established chronic cardiomyopathy (B2-C-D)." (PMID 36447264, 2022). "The increased frequency of CD69+CD4+ T cells suggests a constant activation by remaining parasites or antigens that persist into the Chagas disease’s chronic phase." (PMID 36447264, 2022). "Furthermore, B1 has a unique expression of CD69 compared to other forms of Chagas disease, more pronounced among naïve T cells." (PMID 36447264, 2022). "Interestingly, despite the expansion of peripheral DP lymphocytes in the experimental model of Chagas disease, these cells develop an activated phenotype, upregulating the activation markers CD44 and CD69, tightly linked to the differentiation status of T cells." (PMID 21858238, 2011). "Unsupervised clustering revealed an increase of CD69+ cells among TN (MC1) and memory (MC4 and MC5) CD4+ T cells in PBMC from patients with Chagas disease." (PMID 36447264, 2022). "Thus, the expansion of CD69+CD4+ T cells during Chagas disease is probably not due to recirculation of TRM." (PMID 36447264, 2022).
endothelial dysfunction (4 papers, 2022 to 2025). In vascular diseases, endothelial dysfunction is a systemic pathological state of the endothelium (the inner lining of blood vessels) and can be broadly defined as an imbalance between vasodilating and vasoconstricting substances produced by (or acting on) the endothelium. "CD69 induction during endothelial dysfunction may drive exaggerated inflammation by antagonizing the endothelial protective S1PR1 pathway." (PMID 40617350, 2025). "In the PVAT, at the earliest time point assessed i.e., 6 h.p.i and prior to endothelial dysfunction there was a significant but small elevation in CD69 and IFN-γ but no change in TNF-α, IL-6, or NOX2." (PMID 35930608, 2022).
gastric cancer (4 papers, 2020 to 2023). A primary or metastatic malignant neoplasm involving the stomach. "However, the roles of SFRP2+ fibroblasts, MYH11+ fibroblasts, CD234+ endothelial cells and CD69+ fibroblasts are not clear in gastric cancer." (PMID 37649598, 2023). "For example, while PD-1hi CD8+ Trm cells highly express cell adhesion and tissue positioning markers, including CD69 and integrins CD11c, CD49a, CD49b, and CD103 in HCC, CD103+CD8+ Trm cells express tissue residency-promoting molecules, such as CD69, CD49a, and RUNX3, in gastric cancer." (PMID 35096624, 2021).
heart failure (4 papers, 2021 to 2023). Inability of the heart to pump blood at an adequate rate to meet tissue metabolic requirements. "Consistently, clinical data from 2 independent cohorts of patients indicated that increased CD69 expression in peripheral blood cells after acute MI was associated with a lower risk of rehospitalization for heart failure (HF) after 2.5 years of follow-up." (PMID 36066993, 2022). "Consistently, clinical data from two independent cohorts of patients indicated that increased CD69 expression in peripheral blood cells after acute myocardial infarction was associated with a lower risk of rehospitalization for heart failure after 2.5 years of follow-up." (PMID 37373979, 2023). "Finally, in the clinical setting, we found that Tregs with low CD69 expression after acute MI were associated with an increased risk of rehospitalization for heart failure (HF) at mid-term follow-up." (PMID 36066993, 2022). "CD69 has also been identified as being inhibitory to cardiac inflammation and heart failure progression in autoimmune myocarditis." (PMID 34153003, 2021).
Insulin resistance (4 papers, 2021 to 2025). Increased resistance towards insulin, that is, diminished effectiveness of insulin in reducing blood glucose levels. "CD69+iNKT positively correlated with insulin resistance, aspartate aminotransferase (AST) level, liver fibrosis-4 index (FIB4) and AST to Platelet Ratio Index (APRI)." (PMID 35052736, 2021). "Furthermore, insulin-specific CD8 T cells from high-H exhibited increased expression of the activation markers CD69 and LAG3 compared to bulk CD8 T cells, but not to low-H individuals, suggesting that their activation is independent from insulin resistance." (PMID 39656436, 2025).
latent infection (4 papers, 2015 to 2025). "Our results also revealed differences between IFNG and TNFA induction profiles and greater proportions of CD4+CD69+ T cells producing TNFA (but not IFNG) during active TB relative to latent infection." (PMID 30283456, 2018). "The inhibition of HIV latent infection of resting T cells did not result from possible drug cytotoxicity, because the short drug treatment did not inhibit T cell function, as judged by the surface expression of CD25 or CD69 following T cell activation." (PMID 28381571, 2017).
multiple sclerosis (4 papers, 2020 to 2025). A progressive autoimmune disorder affecting the central nervous system resulting in demyelination. "Similarly, in multiple sclerosis, CD8+ T cells from active lesions exhibit a tissue-resident memory phenotype (CD69, CD103, PD-1, CD49a) associated with an intermediate expression of GPR56 without granzyme B expression." (PMID 35831277, 2022).
nasal polyps (4 papers, 2021 to 2024). "Research has shown that eosinophils from nasal polyps exhibit elevated levels of CD69 mRNA, a marker of cellular activation, compared to peripheral blood eosinophils, indicating that the eosinophils in nasal polyps are activated." (PMID 37934391, 2023). "Importantly, in the same patients with ECRS, CD69 expression on eosinophils was extremely elevated in nasal polyps compared with that in peripheral blood." (PMID 34356851, 2021). "Similarly, in our previous paper, we showed a high CD69 expression in activated human eosinophils in nasal polyp tissues obtained from patients with ECRS but none in the peripheral blood." (PMID 38540778, 2024).
pneumonia (4 papers, 2022 to 2026). An acute, acute and chronic, or chronic inflammation focally or diffusely affecting the lung parenchyma, caused by an infection in one or both of the lungs (by bacteria, viruses, fungi, or mycoplasma.). "Our data revealed that γδ T cells in the lungs of animals surviving neonatal pneumonia exhibited an activated CD69+CD44+CD62L- profile, consistent with tissue-resident effector T cells." (PMID 41011451, 2025).
respiratory infections (4 papers, 2018 to 2022). "Respiratory infection promotes formation of mucosal TRM cells which express CD103 in combination with CD69." (PMID 31258537, 2019). "Therefore, Tmem located in the lung parenchyma after respiratory infection lack one of the key attributes associated with bona fide TRM, expression of CD69 and CD103." (PMID 29403499, 2018). "Considering the growing number of studies demonstrating the importance of resident memory T cells (TRM) in protection against respiratory infections, the cells in the BAL and lungs were analyzed for canonical residency markers CD69 and CD103." (PMID 35337006, 2022). "It is also possible that respiratory infections alter TRM programming via inhibition of CD103 and CD69 expression, which negatively affects the formation and/or retention of TRM cells in the respiratory tract." (PMID 29403499, 2018). "Therefore, an inferior CD69+CD103+ TRM response underpins loss of heterosubtypic immunity in the lung and raises the question of why long-lived, stable TRM does not form in the lung following respiratory infection." (PMID 29403499, 2018).
skin infection (4 papers, 2019 to 2022). An inflammatory process affecting the skin, caused by bacteria, viruses, parasites, or fungi. "We and others have shown that following activation, naïve antigen-specific CD8+ T cells differentiate into largely CD69+/CD103+ TRM after the resolution of VacV skin infection." (PMID 30875408, 2019). "Deficiency of dedicator of cytokinesis 8 (DOCK8), a protein involved in regulating the cell actin skeleton, was found to decrease the numbers of CD69+ and CD103+ TRMs surviving in the skin after skin infection." (PMID 34445713, 2021). "In a skin infection model, infiltrating CD8+ T cells, but not CD4+ T cells, upregulate CD69 on their cell surfaces after skin entry which serves to retain the cells in the skin and later differentiate into resident memory T cells." (PMID 36275685, 2022).
anemia (3 papers, 2014 to 2021). A reduction in the number of red blood cells, the amount of hemoglobin, and/or the volume of packed red blood cells. "CD69 has been found to be upregulated after intestinal bacterial exposure and downregulated in murine models with severe anemia." (PMID 34746064, 2021). "Additionally, we noted an association between anemia (Hb ≤ 12 g/dL) and higher concentrations of β2M with increased frequencies of CD4+CD69+ T cells (p = 0.08 and p = 0.02, respectively)." (PMID 34502204, 2021).
aneurysm (3 papers, 2019 to 2025). Bulging or ballooning in an area of an artery secondary to arterial wall weakening. "We also expand on these earlier findings by demonstrating that the majority of CD4+ and CD8+ T cells present within the aneurysm positively express CD69 as well as showing expression of other activation markers including HLA-DR+ and CCR5." (PMID 31552015, 2019).
bladder cancer (3 papers, 2014 to 2024). "Increased CD69 expression on CD155Bi-Ab-ATC over their unarmed ATC after incubation with bladder cancer cells were detected by FACS." (PMID 31602268, 2019). "This is in line with the results obtained in ovarian and urinary bladder cancer specimens using Ig-class-switch or CD69-positivity to characterize activated B cells." (PMID 25026291, 2014).
brain ischemia (3 papers, 2017 to 2021). Diminished or absent blood supply to the brain caused by obstruction (thrombosis or embolism) of an artery resulting in neurologic damage. "In the brain, miR-1224 transiently suppressed CD69 expression and IFN-γ release at day 1 after MCAO but did not significantly impact NK cell counts or NK cell activation after day 1 of brain ischemia." (PMID 34118948, 2021).
chorioamnionitis (3 papers, 2011 to 2020). A morphologic finding indicating inflammation of the fetal sac membranes. "Babies who had an unstable course or those born in the context of chorioamnionitis showed elevated levels of the activation marker CD69 on all T cell populations (CD4, CD8 and γδ) as well as on NK cells when compared to babies who had a stable postnatal course." (PMID 32152273, 2020).
chronic hepatitis (3 papers, 2011 to 2024). An active inflammatory process affecting the liver for more than six months. "Thus, the liver environment of untreated chronic infection as well as chronic hepatitis patients is characterized by a high accumulation of CD8+ T cells expressing CD69 and PD-1." (PMID 39882238, 2024). "First, we showed that untreated cHBV patients, in both the chronic infection and chronic hepatitis phases, are characterized by an accumulation of CD8+ T cells that highly express the activation marker CD69." (PMID 39882238, 2024).
eosinophilia (3 papers, 2020 to 2022). "In comparison, trehalose did not affect LPS‐mediated upregulation of CD69 on mouse blood eosinophils and mRNA levels of IL‐5 and IL‐13 in human eosinophilic cell line, suggesting that trehalose may not directly act on eosinophils to alleviate eosinophilia." (PMID 35988262, 2022).
fibrosis (3 papers, 2013 to 2024). the formation of excess fibrous connective tissue in an organ or tissue in a reparative or reactive process. "A lower expression of CD69 on eosinophils has been shown in patients with chronic intestinal schistosomiasis when compared to those with periportal fibrosis." (PMID 24348679, 2013). "The majority of T cells present in the skin infiltrate were activated T lymphocytes, suggesting that early CD69+ T cells may actively participate in cell-cell contact with fibroblasts to induce fibrosis in skin lesions." (PMID 29669578, 2018). "Moreover, flow cytometry revealed increased expression levels of CD69 and CXCR6 in pulmonary CD4 T cells during fibrosis progression." (PMID 38789926, 2024).
Granuloma (3 papers, 2022 to 2024). A compact, organized collection of mature mononuclear phagocytes, which may be but is not necessarily accompanied by accessory features such as necrosis. "By comparing all of the tetramer+ cells to tetramer− cells in individual granulomas, we observed higher frequencies of T-bet, RORγT, and CD69 as well as significantly lower levels of PD-1 in the tetramer+ cells." (PMID 37039646, 2023). "We found that granulomas were enriched sites for Mtb-specific cells and that tetramer+ cells had increased frequencies of the activation marker CD69 as well as the transcription factors T-bet and RORγT, compared to tetramer negative cells within the same sample." (PMID 37039646, 2023). "The most abundant subcluster (8.3% of granuloma cells, q = 0.074, Dirichlet p = 0.00049) exhibited elevated expression of markers of naive and memory T cells (TCF7, CCR7, IL7R, and TXNIP) and activation or memory state (CD69 and ITGB1)." (PMID 35483355, 2022).